ZNF551 (zinc finger protein 551)
Description:
May be involved in transcriptional regulation.
Synonyms: DKFZp686H1038
Tractability: PROTAC: UniProt records ubiquitination sites on it; ubiquitination databases record sites on it.
Gene: Protein-coding gene on chromosome 19 (57,681,969 to 57,717,301, forward strand). Ensembl gene ENSG00000204519.
Subcellular location: Nucleus
Subcellular location (Human Protein Atlas): Nuclear speckles; Nucleoplasm
Pathways (Reactome):
Gene expression (Transcription): Generic Transcription Pathway
Gene Ontology:
Molecular function: DNA-binding transcription factor activity, RNA polymerase II-specific; RNA polymerase II cis-regulatory region sequence-specific DNA binding
Biological process: regulation of transcription by RNA polymerase II; negative regulation of DNA-templated transcription; regulation of DNA-templated transcription
Cellular component: nucleus
Genetic constraint (gnomAD): Loss-of-function variants: 5 observed, 8.13 expected, observed/expected ratio (o/e) 0.61, 90% interval 0.32 to 1.29. That is too few expected variants to judge how well the gene tolerates losing a copy. Missense variants: 788 observed, 855.79 expected, observed/expected ratio (o/e) 0.92, 90% interval 0.87 to 0.98. Synonymous variants: 287 observed, 285.74 expected, observed/expected ratio (o/e) 1, 90% interval 0.91 to 1.11.
Homologues: Orthologues: chimpanzee ZNF551 (99% identical), macaque ZNF551 (96% identical), mouse Zfp551 (63% identical), rat Zfp551 (63% identical). Paralogues in human: ZNF418 (46% identical), ZNF792 (46% identical), ZNF256 (45% identical), ZNF304 (45% identical), ZNF587B (44% identical), ZNF549 (41% identical), ZNF548 (40% identical), ZIK1 (39% identical), ZNF772 (35% identical), ZNF586 (35% identical), ZNF583 (34% identical), ZNF773 (33% identical), and 26 more.